CRP (C-reactive protein)
Diseases named in the same sentence as CRP in open-access papers (continued):
Sharing a sentence is not in itself a finding about the gene and the disease.
diabetes (continued). "In a retrospective cohort study of 60 critically ill patients in Wuhan, diabetes, emphysema, higher CRP, neutrophil-to-lymphocyte ratio, and medial or parahilar lung involvement in CT scan were associated with higher death rates." (PMID 34306751, 2021). "As there are few studies on this topic, especially in the Indian population, we intend to study high sensitivity CRP in pre-diabetes in the central Indian rural population." (PMID 34868746, 2021). "In unadjusted Cox survival analysis, hospital mortality was associated with age, sex, ACCI score, frailty category, CRP, creatinine, CKD, diabetes, and dyspnoea or fever as presenting complaints." (PMID 33564474, 2021). "Old age, diabetes mellitus, smoking, and several laboratory values, such as RDW-CV and CRP, were independently associated with increased mortality." (PMID 33782522, 2021). "Subjects with diabetes had significantly higher phosphate, albumin, C-reactive protein, brain natriuretic peptide and sclerostin levels (61.1 vs 39.3 pmol/L, P = 0.035), compared to those without diabetes." (PMID 34644326, 2021). "The results revealed that the prognosis was related to diabetes mellitus, CRP, NT-pro BNP, and hs-cTnI levels (all P < 0.05 or P < 0.01)." (PMID 34580597, 2021). "Under physiological conditions, the level of CRP synthesis is low, however, the production increases in inflammation and it is observed in many inflammatory diseases, including diabetes." (PMID 33504108, 2021). "Patients with the higher hs-CRP quartile were more likely to be elder, female and have a history of diabetes." (PMID 34109224, 2021). "A significant increase in the concentrations of the markers was already found in the patients with newly diagnosed diabetes mellitus, i.e., at a very early stage of the disease, while the systemic inflammation index (CRP) was normal." (PMID 34768589, 2021). "After adjusting for age, sex, hs-CRP, BMI, diabetes, smoking, and educational level, the relationships of AF with severe PD and BOP were no longer significant." (PMID 34807935, 2021). "The low IL-37, diabetes mellitus, high CRP, NT-pro BNP, and hs-cTnI in the blood were included in the analysis, and the occurrence of cardiovascular events was taken as the dependent variable." (PMID 34580597, 2021). "We finally identified the following 10 variables with the strongest association with stroke risk: sex, age, SBP, CRP, ESR, TC, LDL, and history of hypertension, diabetes, AF, and CHD." (PMID 34081620, 2021). "In this study, we found high sensitivity CRP as a definite predictor of inflammation in pre-diabetes, which was the primary outcome." (PMID 34868746, 2021). "A previous study found that probiotic and synbiotic administration had a significant effect on CRP levels in individuals with diabetes." (PMID 34955840, 2021). "Previous studies have reported that there is a relationship between higher levels of circulating C-reactive protein, related to adiposity and diabetes." (PMID 34831711, 2021). "CRP is significantly elevated in patients with diabetes, and recent studies found that females with diabetes exhibit higher levels of CRP than males." (PMID 34829890, 2021). "Subgroup analyses were performed to examine potential effect modifiers, stratified by age, BMI, waist circumference, CRP, diabetes status, and physical activity." (PMID 33731171, 2021). "It is generally accepted that inflammation cytokines like the C-reactive protein (CRP) are a determinant for the connection between diabetes and periodontitis." (PMID 33804123, 2021). "“Large neck” patients had a significantly higher prevalence of hypertension (63 vs. 48%), diabetes (33 vs. 19%), obesity (26 vs. 14%), and elevated C-reactive protein (CRP) (98 vs. 88%)." (PMID 34940406, 2021). "C-reactive protein (CRP) is another inflammatory marker that increases in diabetes; indeed, CRP is considered the best epidemiological marker of type 2 diabetes (T2DM) associated with cardiovascular diseases nowadays." (PMID 34589130, 2021).
diabetes (continued). "Circulating levels of acute-phase proteins, such as C-reactive protein (CRP), fibrinogen, haptoglobin, and sialic acid, were reported to be augmented in individuals with diabetes." (PMID 34959837, 2021). "Elevations in systemic CRP levels are related to greater incidence of depression, cardiovascular disorders and diabetes, providing a physiological pathway for chronic stress to possibly harm health." (PMID 35010951, 2021). "Diabetes mellitus, coronary artery disease, chronic kidney disease, serum C-reactive protein, and serum lactate dehydrogenase were identified as significant risk factors for ICU transfer, and a prediction model was developed." (PMID 33740030, 2021). "Treatment with Tocilizumab was initiated in 349 patients (9%) with severe evolution, of which 103 (29.5%) with diabetes mellitus selected on the basis of severity criteria: sudden desaturation, increased CRP, ferritin, D-dimers, LDH, and interleukin 6 values." (PMID 34201473, 2021). "Classic CVD risk factors in dialysis patients are prior CVD, higher levels of C-reactive protein (CRP), left ventricular hypertrophy, diabetes, and advanced age." (PMID 34055019, 2021). "The authors conclude that the persistently elevated levels of proinflammatory cytokines and CRP in chronic diabetes result from an ongoing inflammatory process in diabetes." (PMID 33504108, 2021). "Significant independent risk factors for community-acquired AKI were chronic kidney disease (CKD), diabetes, clinical frailty score and admission C-reactive protein (CRP), systolic blood pressure and respiratory rate." (PMID 34301204, 2021). "High blood pressure increases inflammatory markers, such as C-reactive protein, interleukin 6 and adhesion molecules related to the insulin signaling pathway and β-cell function, and further leads to the incident diabetes." (PMID 33926442, 2021). "The best predictors for 1-year adverse events included elevated levels of I-CAM > 239.7 ng/L and an MMP-9 level of over 1155 ng/mL, respectively, after adjustments for diabetes, hs-CRP, acute phase complications and LVEF for the overall study population." (PMID 34362217, 2021). "Among diabetes-free participants in ALSPAC, ABCG1 was positively associated with BMI, waist-circumference, fasting insulin, HOMA scores, CRP and triglyceride levels, but negatively associated with HDL levels." (PMID 33622391, 2021). "Inulin supplementation at 10 g/day in patients with type 2 diabetes mellitus has demonstrated the ability in decreasing weight and BMI with significant decreases in serum high sensitivity-CRP, TNF-α, and LPS." (PMID 34376241, 2021). "Those with elevated CRP had a higher BMI, fewer years of education, were more likely to have smoked and more likely to have hypertension and diabetes." (PMID 34380557, 2021). "Logistic regression analyses indicated that age ≥70 years, diabetes, NYHA grade III, LVEF ≤55%, and CRP ≥10 mg/L were the independent risk factors of pulmonary infections in patients with heart failure (all P < .05)." (PMID 34559121, 2021). "The opposite directions of effect are observed in relation to APOE-ε2 carriers, who have higher levels of CRP and higher incidence of diabetes, but only a nominal increase in aspirin use." (PMID 34301914, 2021). "Age, sex, hypertension, diabetes mellitus, coronary artery disease, chronic obstructive pulmonary disease, CRP, procalcitonin, d-dimer, ferritin, lymphocyte, haemoglobin, APACHE score, and SOFA score were included in the equation." (PMID 33185365, 2021). "Patients with highest quartile of VWF or lowest quartile of ADAMTS13 had an increased age, cardiovascular disease, diabetes mellitus and an increased CRP as compared with highest quartile of VWF or lowest quartile of ADAMTS13, respectively." (PMID 34134634, 2021). "Low grade systemic inflammation lead to early activation of the immune system with supplementary increase in serum CRP and HbA1c in prediabetes leading to frank diabetes." (PMID 33676486, 2021).
diabetes (continued). "The association was borderline significant after adjusted for age, current smoking, alcohol consumption, hypertension, diabetes, BMI, high- sensitive CRP and LDL-cholesterol (OR = 2.25, 95% CI:0.97–5.24, p = 0.06)." (PMID 34600499, 2021). "Under the comorbidities, only diabetes mellitus was a significant risk factor for severity, while high WBC, CRP, LDH, D-dimer and corrected calcium were laboratory parameters associated with severe disease." (PMID 35076497, 2021). "Serum KAL was negatively associated with AAA growth after adjusting for initial AAA diameter, diabetes and serum high sensitive C-reactive protein (hs-CRP) using linear regression (Beta − 0.118, p = 0.036) and logistic regression." (PMID 34465809, 2021). "Higher resistin levels were associated with increased aortic stiffness in patients with coronary artery disease, independently of age, diabetes mellitus, waist circumference, and CRP." (PMID 34202323, 2021). "The other variables associated with increased mortality included age, current smoking, NSTEMI, standardised troponin, serum creatinine, CRP and presence of diabetes mellitus and atrial fibrillation." (PMID 32897534, 2021). "Comparing the groups after adjustment for age, sex, height, MAP, HR, diabetes, eGFR, and CRP revealed that diagnosis group as a significant covariate (P 0.005, partial eta2 = 0.131)." (PMID 34957246, 2021). "TNF- α and CRP are commonly used inflammatory markers in clinic and are positively correlated with the pathogenesis of diabetes." (PMID 33832490, 2021). "Duration of diabetes and hs-CRP level emerged as the strongest predictive variables for elevated baPWV." (PMID 33628837, 2021). "Nonetheless, the relationship between OSAHS and hs-CRP remains under debate, on account of the impact of confounding factors, such as obesity and diabetes." (PMID 33204538, 2020). "Studies have shown that in patients with diabetes and metabolic syndrome, hs-CRP levels are significantly increased, and the increase of hs-CRP levels is associated with insulin resistance and inflammatory responses." (PMID 33028234, 2020). "In the non-diabetes group with CRP ≤10 mg/L, higher CRP Z-score concentrations were significantly associated with higher odds of PAD and nephropathy." (PMID 32665312, 2020). "Chronic periodontitis has been associated with elevated CRP levels, even after controlling for several potential confounders, such as age, education level, gender, smoking, HDL-cholesterol, and diabetes." (PMID 32512870, 2020). "The laboratory findings showed blood glucose levels were higher and that AST or CRP elevation, anemia, and a low albumin level were more frequent in the diabetes group." (PMID 32933191, 2020). "We see improvements in cardiovascular morbidity, respiratory morbidity and anaemia, but deteriorating obesity, diabetes, some biomarkers (fibrinogen and possibly also CRP) and feelings of extreme anxiety/depression." (PMID 32179559, 2020). "Patients with ID were more frequently female, with higher rates of anemia and diabetes, and higher levels of C-reactive protein." (PMID 32331365, 2020). "Although the C-reactive protein (CRP) level was higher in COPD patients with concomitant type 2 diabetes mellitus compared with the second group, the difference was significant only in the CC genotype (p <0.05)." (PMID 33072207, 2020). "Troponin I, CRP, lymphocyte count, shortness of breath, hypertension, hyperlipidemia, diabetes mellitus, and coronary artery disease were analyzed using the multivariate regression model." (PMID 33322097, 2020). "Analyzing various combinations of hsCRP with other criteria, utilizing CRP ≤ 0.2 mg/L or diagnosis of diabetes up to 30 years of age performed best, with 88% sensitivity and 75% specificity." (PMID 32528556, 2020). "Tumor necrosis factor-α and C-reactive protein levels in the blood serum of patients with chronic pancreatitis and type 2 diabetes mellitus, M±m." (PMID 33456608, 2020).
diabetes (continued). "After adjusting for the FFR value, a multivariable analysis showed that gender (p < 0.001), diabetes mellitus (p = 0.005), aortic stenosis (p = 0.016), hs-CRP level (p < 0.001), and eGFR (p = 0.003) were all independent predictors of iFR values." (PMID 32760123, 2020). "Some authors reported a direct relationship between an increased level of CRP and progressing insulin resistance in patients with diabetes mellitus (CRP concentration 3.84 ± 1.45 μg/mL)." (PMID 32326243, 2020). "The diabetes-related vascular complications have been correlated with C-reactive protein (CRP), TNF-α, and IL-6 in the EURODIAB Prospective Complication Study." (PMID 33584278, 2020). "For instance, the patients enroled in the current study exhibited higher prevalence of comorbidities, including diabetes mellitus and hypertension, and higher levels of NT-proBNP; however, the patients exhibited lower levels of CRP and LDL." (PMID 33243972, 2020). "In patients with obesity or diabetes, the adiponectin concentration in the body was inversely related to the C-reactive protein (CRP) concentration; this was also observed in healthy patients presenting no obesity or diabetes." (PMID 33133214, 2020). "In contrast, participants in other groups(Q1-Q3) has higher C-reactive protein and Glycohemoglobin levels, Physical activity, reported a higher incidence of hypertension, Diabetes, coronary heart disease, stroke." (PMID 32359345, 2020). "Low-grade systemic inflammation accompanies diabetes, with high serum levels of C-reactive protein (CRP), tumor necrosis factor (TNF-α), monocyte chemo-attracting protein-1 (MCP-1) and IL-1β." (PMID 32903730, 2020). "Studies in adults have shown a strong relationship of certain metabolic diseases, for example, diabetes, with elevated levels of CRP, TNF-α, and leptin." (PMID 33081030, 2020). "After adjustments for age, C-reactive protein, interleukin-6, procalcitonin, diabetes and hypertension, the highest tertile remained statistically significant, and the relative risk was OR 7.8, 95% CI 2.3–26.4." (PMID 32641174, 2020). "Participants with elevated levels of hs-CRP were older, weighed more, and had a higher incidence of prior hypertension, diabetes, hyperlipidemia, and stroke." (PMID 33363509, 2020). "The increased risk of carotid abnormalities attributable to anti-GRP78 autoreactivity persisted despite adjustment for age, smoking extent, hypertension, diabetes, hyperlipidemia, or levels of CRP, IL-6, and TNF-α." (PMID 32086320, 2020). "The factors included in the predictive nomogram included Sex, diabetes history, anastomotic type, reconstruction route, smoking history, CRP level and presence of cardiac arrhythmia." (PMID 32252738, 2020). "Administering ALA for 4 months to patients with type 2 diabetes mellitus on the background of basic therapy contributes to a significant reduction in CRP by 30.9%, IL-6 by 29.7%, and TNF-α by 22.7%." (PMID 32341698, 2020). "Although inflammation measured by CRP is a known risk factor for CVD, its associations with microvascular and macrovascular dysfunction in diabetes and in non-diabetes are unclear." (PMID 32665312, 2020). "This is the first study assessing the relationship between CRP and diabetes among a sub-Saharan African population." (PMID 32665312, 2020). "Additionally, our finding of an association with higher odds of diabetes and both microvascular and macrovascular dysfunction in non-diabetes individuals implies that CRP could play a role in the assessment of risk before diabetes diagnosis, for example, in pre-diabetes individuals." (PMID 32665312, 2020). "Compared with both control groups, patients with heart failure had lower eGFR, higher CRP, and a higher prevalence of diabetes." (PMID 31923223, 2020). "They suffered more often from hypertension (p = 0.012) and diabetes (p = 0.0001), and presented higher plasma CRP and D-dimer levels (p = 0.002 and 0.017, respectively)." (PMID 33326457, 2020).
diabetes (continued). "GDF-15 levels are independently related to cardiovascular risk factors (diabetes, smoking, low HDL cholesterol) and biochemical risk markers (high-sensitivity C-reactive protein, NT-pro BNP) in elderly individuals and patients with coronary heart disease." (PMID 32466218, 2020). "For instance, age was related to waist circumference and smoking and drinking status, and metabolic syndrome was directly connected with diabetes and hs-CRP." (PMID 33123092, 2020). "CRP shows high correlation with metabolic syndrome, diabetes and CDV, and fibrinogen leads to a prothrombotic state." (PMID 32466598, 2020). "In multivariate logistic analysis after adjustment for FFR value, gender (p < 0.001), diabetes mellitus (p = 0.005), aortic stenosis (p = 0.016), high-sensitivity CRP (p < 0.001), and renal function (p = 0.003) were all independent predictors of iFR value." (PMID 32760123, 2020). "In both healthy subjects and subjects with diabetes mellitus, honey decreased the levels of plasma glucose, insulin, CRP, total cholesterol, LDL-C, and TG, together with the elevation of HDL-C." (PMID 32455701, 2020). "Similar results were observed when we replaced diabetes with inflammatory markers (i.e., C-reactive protein [CRP], tumor necrosis factor alpha [TNF-α], interleukin-6 [IL-6], and monocyte chemoattractant protein-1 [MCP-1]) or serum albumin concentration." (PMID 32661200, 2020). "C-reactive protein (CRP), a classical inflammatory biomarker, has been considered as an indicative parameter for diabetes and related complications in both cross-sectional and longitudinal studies." (PMID 32612667, 2020). "The Best-fit Risk Score included urinary albumin-to-creatinine ratio, SBP, C-reactive protein, triglyceride, sex, education, and diabetes." (PMID 32252667, 2020). "It is known to be influenced by several factors including age, gender, race, smoking, high CRP levels (defined as higher than 5 mg/L), cardiovascular disease, high blood pressure, and diabetes, although the connection between diabetes and CCS is controversial." (PMID 33390933, 2020). "Since diabetes mellitus (DM) is characterized by an underlying chronic inflammation, hs-CRP may have a different prognostic power in AMI patients with and without DM." (PMID 33081810, 2020). "In the case of independent predictors for all-cause deaths, age, current smoking, diabetes, cancer, COPD, previous stroke, reduced LVEF, lower level of total cholesterol, and higher levels of creatinine and c-reactive protein were found." (PMID 32867290, 2020). "After adjusting for confounding factors (inclusive of lifestyle factors, diabetes, hepatitis infection, and adiposity measures), the incidence rate ratio per doubling of concentration for CRP was 1.22, with 95% CI of 1.02–1.46." (PMID 33256656, 2020). "All patients demonstrated a significant loss of LTM over time, regardless of stratifying the covariates age, sex, LTI, baseline serum CRP, serum albumin, dialysis vintage, diabetes, or comorbidity index." (PMID 32824951, 2020). "The significant risk factors for low ionized calcium levels were higher age, CRP, and iPTH; male sex; lower eGFR, BMI, albumin levels; and diabetes (P < 0.05)." (PMID 32157180, 2020). "Our data from this first study on CRP in relation to diabetes and microvascular and macrovascular dysfunction in a sub-Saharan African population suggest that CRP could be explored as a potential marker to identify sub-Saharan African patients with diabetes at risk for macrovascular complications." (PMID 32665312, 2020). "This increased hazard ratio persisted after adjustment for age, gender and UACR, diabetes, alcohol consumption, CRP, BMI, WHR, cholesterol and triglycerides." (PMID 33261565, 2020). "HD patients had significantly higher levels of serum insulin, higher levels of hs-CRP, and a significantly higher prevalence of diabetes mellitus relative to their control group counterparts (p < 0.05)." (PMID 32274214, 2020).